CXCL10 (C-X-C motif chemokine ligand 10)
Diseases named in the same sentence as CXCL10 in open-access papers (continued):
Sharing a sentence is not in itself a finding about the gene and the disease.
cutaneous melanoma (14 papers, 2019 to 2025). A primary melanoma arising from atypical melanocytes in the skin. "We also found that the metastatic lesions of skin cutaneous melanoma had higher expression level of CXCL10 than the primary lesions." (PMID 34276760, 2021). "Moreover, chemotherapy induces intratumoral expression of CCL5, CXCL9, and CXCL10 in cutaneous melanoma, favoring T cell infiltration and tumor control." (PMID 35292660, 2022). "In skin cutaneous melanoma (SKCM), cancers with high expression of IL1B, CCL5, CXCL10, and TNFSF15 exhibited better prognoses." (PMID 37980406, 2023). "Our correlation analysis of the transcriptomic data of 368 cutaneous melanoma samples revealed a positive correlation of PD-L1 to IFN-γ, STAT-1, IFN-γ driven CXCL10 and CXCL9 as well as to acidosis driven MMP9." (PMID 38102680, 2023). "primarily identified five chemokine members (CCL4, CCL5, CXCL9, CXCL10, CXCL13) as relevant biomarkers in cutaneous melanoma tumorigenesis and progression." (PMID 36713580, 2022). "Patients with high expression of CXCL9, CXCL10, CXCL13, CCL4, and CCL5 in SKCM (Skin cutaneous melanoma) had better overall survival." (PMID 36341437, 2022). "In summary, this study mainly identified five chemokine members (CXCL9, CXCL10, CXCL13, CCL4, CCL5) associated with SKCM tumorigenesis, progression, prognosis and immune infiltrations, which might help us evaluate several immune-related targets for cutaneous melanoma therapy." (PMID 32508531, 2020). "This study analyzed baseline serum levels of CXCL5, CXCL10, and CCL22 in 46 cases of advanced cutaneous melanoma treated with nivolumab." (PMID 31080803, 2019). "Characteristics and serum levels of CXCL5, CXCL10, and CCL22 in patients with cutaneous melanoma." (PMID 31080803, 2019). "Intestinal microbes may influence the proportion of CD8+ CTLs that infiltrated cutaneous melanomas, and Lachnoclostridium is positively correlated with the expression of infiltrated CD8+ CTLs and the chemokines CXCL9, CXCL10, and CCL5 in cutaneous melanoma tissues." (PMID 38515134, 2024).
HCMV infection (14 papers, 2010 to 2025). "In contrast, DOs responded to HCMV infection by secreting both proinflammatory cytokines and chemokines (e.g., CXCL10, MIP-1α, MIP-1β, and IL-6) and through the release of the type III IFN IFN-λ2." (PMID 35975985, 2022). "Taken together, these data suggest that both CCL8 and CXCL10 are produced as a result of the latent HCMV infection of monocytes." (PMID 33912186, 2021). "Increased plasma levels of CXCL10 were reported in context of HCMV infection of lung transplant recipients." (PMID 32093317, 2020). "Notably, PML has been reported to mediate the recruitment of activated STAT1 and 2, along with HDAC1 and 2, onto ISG promoters (ISG54, CXCL10) during human cytomegalovirus (HCMV) infection." (PMID 29309427, 2018). "Human cytomegalovirus (HCMV) infection in human VSMCs activates a novel IκB kinase (IKK)-related pathway involving TBK1, IRF3, and chemokines CCL5/RANTES and CXCL10/IP-10." (PMID 40980176, 2025). "Inhibition of CXCL10, MX1, and OAS1 by UL23 at late times after HCMV infection was observed in this study, so UL23 protects HCMV against the immunomodulatory and antiviral responses of IFN-I." (PMID 34305856, 2021). "Several ISGs, including IFIT1, IFIT2, IFIT3, Mx1, Mx2, CXCL10 and ISG15 were found to be upregulated transcriptionally following HCMV infection independently of type I IFN-initiated JAK-STAT signaling, but dependent on intact IRF3 signaling." (PMID 30871003, 2019). "Induction of the IFN-independent ISG viperin during HCMV infection is known to be induced by either IRF3 or IRF1, binding directly to its promoter, and this may also be the mechanism of IFIT1, IFIT2, IFIT3, CXCL10, Mx1, Mx2 and ISG15 upregulation." (PMID 30871003, 2019). "In murine cytomegalovirus infection and in Toxoplasma gondii infection, early release of CCL3 and CCL4 from APCs is vital for the influx of NK cells into affected tissues, and these cells are an important source of IFN-γ, which induces macrophages and dendritic cells to secrete CXCL9 and CXCL10." (PMID 20828409, 2010).
hepatitis B (14 papers, 2013 to 2024). "Of note, CXCL10 values were high in patients with acute hepatitis B and low in healthy controls and NA treated patients with HBV suppression." (PMID 31575964, 2019). "This is an explanation why CXCL10 concentrations are highest in phases of active hepatitis and in patients with acute hepatitis B and, thus, may have an impact as an immunological imprint in the prognosis of the disease." (PMID 31575964, 2019). "In addition, inflammatory neutrophils may directly express CXCL9 and CXCL10, which has been previously shown to impact recruitment of inflammatory T cells in transgenic mice that replicate hepatitis B." (PMID 36248905, 2022). "Topological analysis indicated that AKT1, FOS, CCL2, CXCL8, and CXCL10 are hub genes; TLR signaling pathway, cellular senescence, hepatitis B, and chemokine signaling pathway are key pathways in the IGP network." (PMID 33623529, 2021).
metastatic melanoma (14 papers, 2015 to 2025). A melanoma that has spread from its primary site to another anatomic site. "Among them, CD8A, SOX2, TYR, CXCL10 and ICAM1 had the most interaction with other proteins associated with metastatic melanoma." (PMID 39820173, 2025). "The response to immunotherapy and immune cell infiltration were correlated with CXCL10 expression in metastatic melanoma patients, which suggests that CXCL10 is a strong biomarker for a favorable prognosis with immune checkpoint inhibitor (ICI) therapy." (PMID 38928238, 2024). "CXCL10 has been identified as a positive prognostic marker of response to PD-1 immunotherapy in metastatic melanoma." (PMID 39697325, 2024). "A phase I/II clinical trial, investigating tebentafusp (a bispecific fusion protein targeting gp100) in metastatic melanoma patients reported an increase in serum CXCL10 and reduction in circulating CXCR3+ CD8+ T cells." (PMID 37170733, 2023). "We evaluated the correlation of EVI2B gene expression in metastatic melanoma samples with the IFN-γ related gene signature (CXCL10, CXCL9, HLA-DRA, IDO1, IFNG, and STAT1)." (PMID 34439264, 2021). "While intratumoral CXCL10 was identified as a potential favorable prognostic factor in metastatic melanoma, circulating CXCL10 has also been reported to have dual effects and cell growth as well as angiogenesis in cancer, depending on CXCR3 expression and other factors in the TME." (PMID 38236249, 2024). "In metastatic melanoma, intratumoral CXCL10 exhibited a good prognosis by recruiting T cells." (PMID 37048082, 2023). "In addition, BIN2, CMTM8, CXCL10, HCLS1, ITGB2, PTPN2, and RFTN2 were expressed at significantly higher levels in our B16 brain-derived variants compared with the parent B16-F0 and are also upregulated in human metastatic melanomas compared with primary cutaneous tumors." (PMID 39819494, 2025). "A study looking at metastatic melanoma biopsies showed that up-regulation of several chemokines, including CCL2, CCL3, CCL4, CCL5, CXCL9, and CXCL10 could be correlated with the presence of T cells in the tumor." (PMID 34207884, 2021).
psoriatic arthritis (14 papers, 2006 to 2025). Joint inflammation associated with psoriasis. "Moreover, CXCL10 is typically a chemokine found in high concentrations in synovial fluids from inflammatory joints of patients with septic, rheumatoid or psoriatic arthritis." (PMID 28703769, 2017). "Patients with nail involvement had higher CXCL10 expression; longer duration of the disease was associated with further decrease of CCL27 in areas that were not affected with psoriatic rash; and psoriatic arthritis was associated with lower IFIH1 expression." (PMID 28790368, 2017).
Sjögren’s syndrome (14 papers, 2010 to 2025). "Our findings suggest CXCL10 as a possible disease biomarker in primary Sjögren’s syndrome due to its upregulated expression in both saliva and minor salivary glands of patients and the localization in the tissue." (PMID 39436967, 2025). "Finally, the chemokine CXCL10 (IP-10) involved in the pathogenesis of many auto-immune disease including Sjögren syndrome seems to be increased during the flares-up in TAFRO." (PMID 29018798, 2017). "We have previously shown significantly upregulated levels of CXCL10 and CCL3 chemokines in saliva from Sjögren’s syndrome patients." (PMID 39436967, 2025). "CXCL9 protein levels (along with CXCL10 and CXCL11) were elevated in tears and conjunctival epithelium from Sjögren syndrome patients compared to controls samples." (PMID 30347820, 2018). "Pro-inflammatory cytokines IL-1β, IL-6, IL-17 and TNF-α, as well as chemokines CXCL8, CXCL10, and CXCL13 are significantly elevated in the saliva of patients with Sjögren’s syndrome compared to healthy controls, and that their levels are correlated with the activity and severity of disease." (PMID 38714918, 2024). "This study aimed to investigate the serum and expression levels of C-X-C motif chemokine ligand 9 (CXCL9), CXCL10, CXCL11, and CXC receptor 3 (CXCR3) in minor salivary glands (MSGs) of patients with primary Sjögren’s syndrome (pSS), and to explore their correlations with clinical parameters." (PMID 38900301, 2024). "In this study, we found an upregulation of CXCL10 and CCL3 in Primary Sjögren’s syndrome (pSS) patients compared with non-SS sicca controls." (PMID 39436967, 2025). "Significantly increased IP-10/CXCL10 expression in both corneal and conjunctival epithelium has been described in an experimental animal model of dry eye and more recently in tears from Sjögren Syndrome DED patients, and also, but non significantly, in non-Sjögren DED patients." (PMID 20508732, 2010).
dermatitis (13 papers, 2015 to 2025). An inflammatory process affecting the skin. "HBZ-Tg/CXCL10 KO mice developed dermatitis beginning at 12 weeks old." (PMID 26296091, 2015). "In this process, chemokines induced by interferon‐g (such as CXCL9, CXCL10, and CXC11) play a significant role in attracting inflammatory cells to infiltrate the interface dermatitis." (PMID 38799517, 2024). "In this study, immunofluorescence and qPCR analysis showed that MLT significantly reduced the infiltration of CD4+ T cells in rosacea-like dermatitis and suppressed the expression of Th1-related genes (IFN-γ, CCR5, CXCL9, CXCL10) and Th17-related genes (STAT3 and IL-20) in rosacea-like dermatitis." (PMID 34899707, 2021). "However, a similar dichotomy in the expression of CXCL9 and CXCL10 (and CXCL11) has been described before for different human skin disorders." (PMID 31447864, 2019). "Chemokine genes, including CXCL9 and CXCL10, which are regulated by T-cell effector cytokines, exhibit different levels of upregulation in hapten-specific skin inflammation but are not induced during irritant-induced skin inflammation." (PMID 37513911, 2023). "Although CD4+ T cells from HBZ-Tg mice and HBZ-Tg/IFN-γ KO mice were similar in their migratory responses to CXCL10, their abilities to infiltrate tissues in vivo may differ, because the HBZ-Tg/IFN-γ KO mice did not develop dermatitis to the same degree that the HBZ-Tg mice did." (PMID 26296091, 2015).
Graves disease (13 papers, 2014 to 2025). Graves' disease is an autoimmune disorder that leads to overactivity of the thyroid gland (hyperthyroidism).It is caused by an abnormal immune system response that causes the thyroid gland to produce too much thyroid hormones. "Collectively, it is hypothesized that if the anti-FSC antibody has a stimulating ability to promote IL-6 or CXCL10 secretion from FSCs like TSH receptor antibody does in Graves’ disease, a functional impairment of corticotroph may occur, resulting in acquired IAD." (PMID 33679614, 2021). "IFN−γ induces helper T cell (Th) 1 in the thyroid and activates macrophages via increased expression of C-X-C motif chemokine ligand 10 (CXCL10), a cytokine elevated in the active phase of Graves disease, in thyroid cells." (PMID 39882352, 2025).
Hyperglycemia (13 papers, 2016 to 2025). An increased concentration of glucose in the blood. "Conversely, hyperglycemia causes CXCL10 release from human monocytes via the Toll-like receptor (TLR) 2 and TLR 4 pathway." (PMID 29544513, 2018). "Hyperglycemia in neonatal rats can induce CXCL10/CXCR3 signaling, microglial activation, and astrocyte proliferation, altering long‐term synaptic formation and function in the hippocampus." (PMID 40130458, 2025). "In this analysis, levels of IL-10, IL-10/TNF-α ratio, and CXCL10 were found to be independent predictors of stress hyperglycemia as defined by a SHR of more than 1.14." (PMID 36059840, 2022). "Neonatal hyperglycemia induces CXCL10/CXCR3 signaling, microglial activation, and astrocytosis in the rat hippocampus and alters long-term synaptogenesis and behavior." (PMID 29544513, 2018). "Our present study confirms a similar response in the hippocampus and demonstrates the novel finding that hyperglycemia upregulates the CXCL10/CXCR3 signaling pathway." (PMID 29544513, 2018). "In summary, we found that hyperglycemia in newborn rats induces CXCL10/CXCR3 signaling, microglial activation, and astrocytosis, and alters long-term synaptogenesis and function in the hippocampus." (PMID 29544513, 2018). "Consistent with this possibility, a previous study demonstrated that blockage of NF-kB with IkB abrogates hyperglycemia-induced CXCL10 release from monocytes." (PMID 29544513, 2018). "Our findings may align with previous studies showing that hyperglycemia promotes the expression of CXCL10 and CXCL11 on Schwann cells, recruiting CXCR3‐expressing CD8+ lymphocytes and leading to apoptosis of the Schwann cells." (PMID 37021432, 2023). "Upregulation of these markers in the recurrent hyperglycemia model rules out STZ as the primary cause of CXCL10/CXCR3 upregulation." (PMID 29544513, 2018). "For example, in condition of hyperglycemia, EVs derived from platelet-rich plasma (PRP) can induce retinal endothelial injury by transferring CXCL10 and upregulating the TLR4 signaling pathway." (PMID 38389842, 2024). "On P6, the transcript and protein expression of markers of oxidative stress and inflammatory cytokines, including the CXCL10/CXCR3 pathway, were upregulated in the hyperglycemia group." (PMID 29544513, 2018). "In addition, hyperglycemia enhances NF-κB signaling pathway—increased NF-κB and its co-activator PARP1 expression—and also promotes the overexpression of CXCL10 by neurons, microglia and astrocytes, and its receptor CXCR3, expressed by neurons and microglia." (PMID 36869375, 2023). "Under some abnormal conditions, i.e., chronic hyperglycemia, the system fails to restore homeostasis and allows an overproduction of inflammatory cytokines/chemokines, including CXCL10." (PMID 35712355, 2022). "Log IL-10, IL-10/TNF-α ratio, and log CXCL10, but not log IFN-γ were independently associated with stress hyperglycemia." (PMID 36059840, 2022). "Although this pathway is implicated in the pancreatic β cell destruction in T1D and serum CXCL10 is considered a biomarker of T1D in adult humans, to our knowledge, this is the first demonstration of CXCL10/CXCR3 upregulation in the hippocampus due to hyperglycemia." (PMID 29544513, 2018). "Whether hyperglycemia affects CXCL10/CXCR3 signaling in the developing hippocampus is not known." (PMID 29544513, 2018). "Patients with stress hyperglycemia had significantly higher levels of IL-10, IL-10/TNF-α ratio, CXCL10, and CRP than patients without stress hyperglycemia." (PMID 36059840, 2022). "Conversely, in the absence of metformin, CXCL10 and TIMP1 gene expression was significantly upregulated under hyperglycemia–hypoxia versus hyperglycemia." (PMID 26861446, 2016).
hypothyroidism (13 papers, 2009 to 2025). Abnormally low levels of thyroid hormone. "We identified that genetic susceptibility to hypothyroidism raises plasma CXCL10 expression levels, and CXCL10, in turn, increases the risk of IPF." (PMID 39185418, 2024). "This study marks a significant advancement in the field of metabolic disease research by elucidating the genetic relationships among hypothyroidism, T2D and hypoglycaemia, with a particular focus on the rs2476601 variant and the role of the immune system, especially the inflammatory protein CXCL10." (PMID 39238070, 2024). "Our study revealed that susceptibility to hypothyroidism elevates plasma CXCL10 expression, leading us to speculate that chemokines may act as a bridge linking thyroid dysfunction with pulmonary tissue remodeling and fibrosis in IPF." (PMID 39185418, 2024). "CXCL10 may be a marker of a more powerful and more aggressive inflammatory response in the thyroid or cause destruction of thyroid tissues and hypothyroidism." (PMID 29383139, 2017). "In summary, our research presents compelling evidence that CXCL10 is a critical mediator in the nexus between hypothyroidism and IPF." (PMID 39185418, 2024). "To address this gap, we plan to utilize the UK Biobank cohort to further explore the relationship between hypothyroidism, CXCL10, and IPF." (PMID 39185418, 2024). "Mediation analysis revealed that CXCL10 accounted for 36.45% of the impact of hypothyroidism on IPF." (PMID 39185418, 2024). "We conducted an independent analysis using an external dataset for CXCL10 to evaluate its impact on hypothyroidism and IPF." (PMID 39185418, 2024). "To further elucidate the functional roles of the instrumental variable SNPs for hypothyroidism and CXCL10, we analyzed the candidate genes corresponding to each rsID." (PMID 39185418, 2024). "We selected 131 and 75 SNPs as instrumental variables for two different hypothyroidism datasets, 632 SNPs for 26 proteins (including 21 SNPs for the CXCL10 external validation dataset), 45 SNPs for TSH, 24 SNPs for FT4, 4 SNPs for TPOAB concentration, and 23 SNPs for IPF." (PMID 39185418, 2024). "Specifically, the results were as follows: CXCL10‐hypothyroidism/myxoedema (β = 0.016, p = 0.045), hypothyroidism/myxoedema‐CXCL10 (β = 0.971, p = 0.0006), CXCL10‐T2D (β = 0.079, p = 0.036), T2D‐CXCL10 (β = −0.038, p = 0.017) and CXCL10‐hypoglycaemia (β = 0.307, p = 0.029)." (PMID 39238070, 2024). "The findings suggest that hypothyroidism, through altered plasma protein expression, particularly CXCL10, may contribute to the pathogenesis of IPF." (PMID 39185418, 2024). "Our utilization of MR analysis not only further confirmed the genetic relationship among hypothyroidism, T2D and hypoglycaemia but also verified the potential key role of immune‐related inflammatory protein factors, such as CXCL10, in the development of these diseases." (PMID 39238070, 2024). "The activity of the thyroid and thyroid autoantibodies had no impact on the expression of these proteins, indicating that CXCL10 may be a key mediator protein in the impact of hypothyroidism on IPF." (PMID 39185418, 2024). "In this study, utilizing MR analysis for the first time, we discovered that hypothyroidism can lead to changes in the expression levels of 26 plasma proteins, including CXCL13, VAMP1, and CXCL10, among which CXCL10 may mediate the impact of hypothyroidism on the risk of developing IPF." (PMID 39185418, 2024). "This novel insight highlights the potential of CXCL10 as a therapeutic target in IPF, especially in patients with hypothyroidism." (PMID 39185418, 2024). "The presence of higher CXCL-10 serum levels is more common in patients with CAT than in healthy individuals, and even after the correction of hypothyroidism by levothyroxine, there is no significant reduction of CXCL-10." (PMID 23316383, 2012).